LILRB4 (leukocyte immunoglobulin like receptor B4)
Diseases named in the same sentence as LILRB4 in open-access papers (continued):
Sharing a sentence is not in itself a finding about the gene and the disease.
tumor (continued). "In primary AML, leukocyte immunoglobulin-like receptor B4 (LILRB4) is highly expressed (its expression level is 40–50 times higher than that of PD-L1 and PD-L2 in AML) and promotes tumor infiltration through suppressing T cell activity and triggering immune evasion beyond PD-L1 and L2." (PMID 36226062, 2022). "There was a decrease in tumor burden and prolonged survival of tumor-challenged mice lacking LILRB4 (LILRB4−/−) compared with WT control." (PMID 33974041, 2021). "We examined the expression of LILRB4 on tumor-infiltrating immune cells at different stages of tumor development and observed that LILRB4 expression increased on CD45+ cells as B16/F10 tumor progressed (day 14 tumor versus day 21 tumor)." (PMID 33974041, 2021). "We also observed LILRB4 expression exclusively on tumor-infiltrating immune cells and not on splenic immune cells." (PMID 33974041, 2021). "Results from the xenograft model corroborated our hypothesis that inhibiting LILRB4 substantially reduced tumour weight and slowed xenograft growth, with no observed difference in body weight in the mice." (PMID 40576161, 2025). "Additionally, LILRB4 + MM cells communicate with monocytes through the SPP1/CD44 axis, which likely contributes to the regulation of the monocyte–macrophage system within the tumor microenvironment." (PMID 41417876, 2025). "The humanized monoclonal antibody, chimeric antigen receptor T (CAR-T) cells and the antibody drug conjugates (ADC) that specifically targeted LILRB4 could significantly inhibit the progression of AML, therefore, LILRB4 has been as a potential target for tumor therapy." (PMID 38951916, 2024). "It has been reported that LILRB4 coordinates MDSC polarization by inducing the differentiation of M-MDSCs toward a tumor-promoting M2 phenotype, and that high expression of LILRB4 decreases the expression of anti-tumor miRNAs in MDSCs, including miR-1a-3p, miR-133a-3p and miR-206-3p." (PMID 38397424, 2024). "The ability of anti-LILRB4 to restore IL-2 production in HDVax-induced CD4+ T cells prompted us to ask whether IL-2 supplementation would restore effector CD8+ T cell function and tumour rejection." (PMID 39048822, 2024). "In NSCLC, LILRB4 recruits SHP-2 and SHP-1, which results in subsequent ERK1/2 signaling activation, mediating the epithelial–mesenchymal transition (EMT) and increasing vascular endothelial growth factor (VEGF-A) expression in NSCLC cells in support of tumor cell invasion and angiogenesis." (PMID 38397424, 2024). "Similarly, whereas transfer of HDVax-induced cluster 3 cells from WT mice suppressed tumour rejection in this assay, transfer of CD25−CD200−CD39+ cluster 3 cells from Lilrb4−/− mice did not inhibit tumour rejection." (PMID 39048822, 2024). "However, the expression pattern of LILRB4 in most tumor cells has not been reported." (PMID 38951916, 2024). "The expression of LILRB4 on CD11c+ DCs, NK cells, and NKT cells was not very high; tumor-infiltrating B cells did not express LILRB4." (PMID 33974041, 2021). "After 40 days of tumor injection, 3 out of 6 mice (50%) died in isotype and only BTZ treated groups, 1 mouse (16.67%) died in anti-LILRB4-treated group, and no mice died in the combination therapy group (anti-LILRB4 + BTZ)." (PMID 38951916, 2024).
cancer (26 papers, 2009 to 2025). A tumor composed of atypical neoplastic, often pleomorphic cells that invade other tissues. "Our findings suggest that LILRB4 is a potential therapeutic target for mitigating CRD-induced cancer risk in populations exposed to chronic CRD, such as shift workers." (PMID 41102383, 2025). "LILRB4, an immune checkpoint, plays a pivotal role in the development and immune escape of various cancers." (PMID 40576161, 2025). "The Gal-8 protein is robustly expressed in cancer cells and it is a significant enhancer of the LILRB4-mediated immunosuppressive milieu and the growth of tumors." (PMID 38954358, 2024). "LILRB4 plays a vital role in the progression of various cancers, but the mechanism of LILRB4 remains controversial." (PMID 39025844, 2024). "Working through APOE, SHP-2, uPAR, and ARG1 signaling pathways, LILRB4 activation leads to downregulation of T cell activation, aiding in cancer infiltration and immune system evasion." (PMID 39697225, 2024). "Similar to other targets discussed, LILRB4 overexpression in cancer cells compared to normal cells makes it an enticing target for immune checkpoint inhibition and other therapies." (PMID 39697225, 2024). "The addition of a LILRB4 mAb or depletion of sLILRB4 increased T cell reactivity, demonstrating that sLILRB4 in the sera of cancer patients inhibits T cell proliferation." (PMID 38022598, 2023). "One study showed that LILRB4 expressed on MDSCs played a distinct role in inducing immunosuppression in cancer." (PMID 37461040, 2023). "Antibodies blocking leukocyte immunoglobulin like receptor B4 (LILRB4) are being tested as therapeutics for cancer." (PMID 35132958, 2022). "Similar to our CyTOF results, LILRB4 expression on T cells was highly correlated with other inhibitory receptors in both murine tumors and human cancer patient samples analyzed by flow cytometry." (PMID 33974041, 2021). "This is also quite in line with our findings that correlation between LILRB4 expression in tumors and survival in patients is observed but inconsistent among cancers." (PMID 33974041, 2021). "This soluble LILRB4 can damage T-cell responses and block LILRB4 signaling, which is crucial to immunotherapy success in the treatment of malignant tumors." (PMID 31138763, 2019). "High-level expression of the receptors LILRB2 (ILT4) and LILRB4 (ILT3) is a feature of tolerogenic antigen presenting cells and has been observed in cancer and transplant situations." (PMID 19860908, 2009). "Given their potential to inhibit T cell proliferation, LILRB2 and LILRB4 have been studied in the context of allograft tolerance during transplantation and during cancer." (PMID 19860908, 2009). "LILRB4 expression was notably enriched in infiltrating CD45+ cells in BC relative to other cancers." (PMID 40860159, 2025). "Additionally, through intervening with LILRB4 molecules, immune system responsiveness can be adjusted, representing significant value in areas such as cancer treatment." (PMID 38397424, 2024). "Thus, while checkpoint receptors like LILRB4 can be effectively targeted to treat some cancers or revert exhausted CD8+ T cells from mice chronically infected with LCMV, their role in acute infection is complex and should be gauged carefully when using therapeutically." (PMID 35132958, 2022). "LILRB4, LAIR-1 and OSCAR are all members of a larger Leukocyte Immunoglobulin-Like Receptor (LILR) family, several members of which have been described in cancer." (PMID 37662958, 2023). "LILRB4 was highly correlated with IL12RB1 and IL2RB across the various cancer types." (PMID 33974041, 2021). "Signallome analysis suggested that eleven proteins (TPD52, TNFRS17/BCMA, LILRB4/ILT3, TSG101, ZNRF2, UPF3B, FADS2, C11orf38/SMAP, CGREF1, GAA, COG4) were activated only in the sensitive MM cell lines (TK13, 14 and 16 and JJN3), and not in nine other cancer cell lines or in primary monocytes." (PMID 39682151, 2024).
infection (12 papers, 2009 to 2025). The state of being infected such as from the introduction of a foreign agent such as serum, vaccine, antigenic substance or organism. "Moreover, assessment of their metabolic and cytolytic capacity revealed a marked reduction in glucose/oxygen consumption and target cell killing in LILRB4-deficient mice following infection." (PMID 35132958, 2022). "Observations regarding the in vivo role exertion of LILRB4 in two experimental models of allergic inflammation and infection with Ascaris lumbricoides larvae revealed that LILRB4 acts as an inhibitor of allergic inflammatory responses on eosinophils." (PMID 38397424, 2024). "Studies have shown that acute encephalitis caused by a number of viruses, including the neurologic Zika virus ZIKV, leads to an increase in the number of cells in the brain that express LILRB4, which is essential for controlling the infection." (PMID 38397424, 2024). "We found that the expression level of LILRB4 was clearly reduced on human dMDSCs examined by Western blotting and qPCR after infection." (PMID 37461040, 2023). "Together, these suggest an impaired ability of NK cells from LILRB4-KO mice to respond to infection." (PMID 35132958, 2022). "This suggests that LILRB4 expression is required for NK cells to sustain an effective response to infection." (PMID 35132958, 2022). "Compared with WT infection groups, most fetuses from LILRB4-/- infected pregnant mice were evidently smaller and shapeless, placentas were obvious more hemorrhagic and resorbed." (PMID 29643846, 2018). "The abortion rate of LILRB4-/- infected group was significantly increased than that of WT infection group." (PMID 29643846, 2018). "The weight of fetus or placenta from LILRB4-/- infection group was less than that of WT infection group respectively." (PMID 29643846, 2018). "Our finding that LILRB2 and LILRB4 are upregulated in response to Salmonella stimulation indicates that these receptors play a role in limiting the inflammatory response during infection." (PMID 19860908, 2009). "To investigate the biology of LILRB2 and LILRB4 on antigen presenting cells in the context of infection, we infected monocyte-derived macrophages with Salmonella typhimurium transformed with the pFVP25.1-GFP plasmid." (PMID 19860908, 2009). "They express CD62L and CXCR3 and produce large amounts of type I interferons upon stimulation by influenza virus or CD40L, whereas type I interferons often induce upregulation of LILRB4 expression early in infection, which is essential for inhibiting viral proliferation." (PMID 38397424, 2024). "Consistent with this dual effect, our studies show that LILRB4 deficiency exaggerates BMDM responses to IFN-γ and antibody production upon infection but also results in defects in NK cell function that impair viral clearance and may hinder tissue repair." (PMID 35132958, 2022). "The mechanisms by which the defect in NK cells in LILRB4-KO mice becomes more severe during infection are also unknown." (PMID 35132958, 2022). "It has been reported that the LILRB4 expression of decidual macrophages decreased after infection with T. gondii, which induced polarization of classically activated macrophages (M1 macrophages) and inhibited the immune bias of M2 direction, leading to adverse pregnancy outcomes." (PMID 32082272, 2019). "The ability of LILRB2 and LILRB4 to modulate T cell responses could also be of relevance during infection, where skewing of LILRB4 and/or LILRB2 expression might alter the course of an immune response." (PMID 19860908, 2009). "Infection with Salmonella typhimurium or TLR stimulation with Salmonella components led to an upregulation of LILRB2 and LILRB4." (PMID 19860908, 2009). "Here we show that in the absence of LILRB4 signaling, the progression of infection resembled that of WT mice in terms of viral expansion in the CNS, neurological symptoms, and brain lesions early in the disease." (PMID 35132958, 2022).
infection (continued). "While the absence of LILRB4 signaling appears to minimally affect NK cells of healthy mice, during infection fewer NK cells attain a mature phenotype, resulting in impaired cytolytic function." (PMID 35132958, 2022). "In addition, a report suggests increased LILRB4 in activated NK cells during CMV infection and enhanced IFN-γ production by T cells and NK cells upon infection with vaccinia." (PMID 35132958, 2022). "There are relatively few studies regarding these receptors in the context of infection and it is not yet clear how LILRB4 exerts its inhibitory effects." (PMID 19860908, 2009). "Infection of macrophages with Salmonella resulted in an upregulation of LILRB2 and LILRB4." (PMID 19860908, 2009). "Importantly, while C57BL/6 mice developed transient neurological symptoms but survived infection, mice lacking LILRB4/gp49B (LILRB4 KO) exhibited more severe signs of neurological disease and succumbed to disease." (PMID 35132958, 2022).
infectious disease (5 papers, 2009 to 2024). A disorder directly resulting from the presence and activity of a microbial, viral, or parasitic agent in humans. "This highlights a previously unappreciated function of LILRB4 in NK cell development and maturation that may help improve the efficacy of therapies for infectious diseases." (PMID 35132958, 2022). "The differing roles of LILRB2 and LILRB4 on antigen presenting cell biology and in T cell/antigen presenting cell interactions warrant future studies that should prove useful in multiple fields of immunology and infectious disease." (PMID 19860908, 2009).
inflammation (2 papers, 2013 to 2019). Aberrant reaction of the microcirculation characterized by movement of fluid and leukocytes from the blood into extravascular tissues. "Previous study discovered a regulatory role for LILRB4 on DCs in a mouse model of Th2 pulmonary inflammation induced by inhalation sensitization with OVA and LPS." (PMID 31138763, 2019). "More recently, we discovered a regulatory role for LILRB4 on DCs in a mouse model of Th2 pulmonary inflammation induced by inhalation sensitization with OVA and a low dose of LPS followed by inhalation challenge with ovalbumin (OVA) two weeks later." (PMID 23431396, 2013).
neurodegenerative disease (2 papers, 2021 to 2025). A disorder of the central nervous system characterized by gradual and progressive loss of neural tissue and neurologic function. "Leukocyte immunoglobulin‐like receptor B4 (LILRB4) has been shown to be associated with susceptibility to neurodegenerative diseases." (PMID 40702763, 2025). "Emerging evidence indicates the upregulation of LILRB4 expression in several neurodegeneration diseases." (PMID 40702763, 2025). "Consistently, in ALS (a neurodegenerative disease primarily characterized by motor dysfunction), upregulation of LILRB4 expression was observed during disease recovery, suggesting a potential neuroprotective role of LILRB4." (PMID 40702763, 2025). "Several studies have evidenced that LILRB4 is upregulated in neurodegenerative diseases, but the effects of LILRB4 loci on neurodegenerative diseases had not been previously investigated." (PMID 40702763, 2025).
bacterial infection (1 paper, 2009). "In addition to the high level expression that can render antigen presenting cells tolerogenic, there may be a role for lower level expression and activity of LILRB2 and LILRB4 in response to TLR signalling during an immune response to bacterial infection." (PMID 19860908, 2009).
hematologic cancers (1 paper, 2023). "Clinical trials for LAIR-1, LILRB4 and DDR1 in solid and hematologic cancers." (PMID 37662958, 2023).
hematologic malignancies (1 paper, 2024). "Unfortunately, LILRB4 is the only target currently undergoing clinical trial in hematologic malignancies." (PMID 39696628, 2024).
LILRB4 also shares sentences with these, for which no sentence is quoted: Autoimmunity (2 papers); colon carcinoma (2); lung adenocarcinoma (2); neurological disease (2); Parkinson disease (2); Acute Monocytic Leukaemia (1); acute myocarditis (1); acute promyelocytic leukemia (1); bladder cancer (1); brain tumor (1); breast invasive carcinoma (1); cardiovascular disease (1); celiac disease (1); cholangiocarcinoma (1); chronic myelomonocytic leukemia (1); cognitive decline (1); endometrial cancer (1); esophageal cancer (1); glomerulonephritis (1); graft versus host disease (1); head and neck cancer (1); head and neck squamous cell carcinoma (1); hepatocellular carcinoma (1); influenza (1); Insulin resistance (1); kidney (1); latent infection (1); lung squamous cell carcinoma (1); lupus erythematosus (1); myocarditis (1).
A further 8 diseases each share a sentence with LILRB4 in 1 paper.